EMP1 (epithelial membrane protein 1)
Diseases named in the same sentence as EMP1 in open-access papers (continued):
Sharing a sentence is not in itself a finding about the gene and the disease.
pancreatic cancer (4 papers, 2023 to 2025). "In addition, EMP1 was also identified as an independent risk factor for poor prognosis in pancreatic cancer patients after surgery." (PMID 40612666, 2024). "Subsequently, we analyzed the correlation among METTL3 and IGF2BP3 and EMP1 in the pancreatic cancer single-cell dataset." (PMID 41285728, 2025). "Subsequently, infiltration-positive cells were analyzed according to the occurrence of local tissue invasion, METTL3, IGF2BP3 and EMP1 expression levels in pancreatic cancer." (PMID 41285728, 2025). "High expression of EMP1 was associated with poorer overall survival, both in TCGA-PAAD and in pancreatic cancer tissue microarrays." (PMID 41285728, 2025). "We analyzed EMP1 expression in single-cell populations of pancreatic cancer samples and found that EMP1 was predominantly expressed in tumor cells." (PMID 41285728, 2025). "Subsequent Western blotting consistently demonstrated that EMP1 was highly expressed in pancreatic cancer tissues that underwent localized invasion." (PMID 41285728, 2025). "First, we observed that local invasion, METTL3, IGF2BP3 and EMP1 expression levels influence cell infiltration in the pancreatic cancer microenvironment." (PMID 41285728, 2025). "We further explored the role of METTL3, IGF2BP3 and EMP1 in the regulation of the tumor microenvironment in pancreatic cancer." (PMID 41285728, 2025). "The m6A reader IGF2BP3 binds to these sites and stabilizes EMP1 mRNA, enhancing its expression in pancreatic cancer." (PMID 41285728, 2025). "Depletion of EMP1 also severely impaired the metastatic colonization of pancreatic cancer cells, overexpressing IGF2BP3 in mice lung tissue when tumor cells were injected via the tail vein in nude mice." (PMID 41285728, 2025). "We found that local tissue invasion and the level of IGF2BP3 and EMP1 affected the immune cell infiltration in pancreatic cancer by multiple immunofluorescence staining." (PMID 41285728, 2025). "In the EMP1-suppressed group, a reduction in pulmonary metastasis from the tail vein model and hepatic metastasis from orthotopic pancreatic cancer was observed compared to the control group." (PMID 40612666, 2024). "However, this elevated proliferative ability of pancreatic cancer cells was attenuated by inhibiting EMP1 expression." (PMID 41285728, 2025). "Taken together, our results demonstrate the important role of METTL3-IGF2BP3, an m6A modification-recognition regulation combination, in activating the TGF-β/Smads signaling pathway by promoting the stability of EMP1 mRNA and upregulating the expression of EMP1 in pancreatic cancer." (PMID 41285728, 2025). "And IGF2BP3/EMP1 axis may be involved in regulating microenvironmental remodeling in pancreatic cancer." (PMID 41285728, 2025). "In addition, we further explored the effects of knockdown of EMP1 and intervention of the m6A locus in the 3’UTR of EMP1 on the migratory and invasive ability of pancreatic cancer cells in in vivo and in vitro experiments." (PMID 41285728, 2025). "Finally, VASP was identified by mass spectrometry as a protein that specifically binds to EMP1 in pancreatic cancer cells." (PMID 41285728, 2025). "Moreover, in pancreatic cancer, EMP1 protein levels were significantly higher in pancreatic cancers than in paracancerous tissues, as well as in pancreatic cancer samples with local invasion compared to those without local invasion." (PMID 41285728, 2025). "The development of strategies to modulate the activation of the TGF-β/Smads signaling pathway by targeting the IGF2BP3/EMP1/VASP axis may hold promise to improve the current plight of pancreatic cancer." (PMID 41285728, 2025). "Furthermore, we analyzed the effects on EMP1 mRNA stability after METTL3 knockdown or overexpression and showed that overexpression of METTL3 in pancreatic cancer cells increased the stability of EMP1 mRNA, and consistently, the stability of EMP1 mRNA was inhibited after METTL3 knockdown." (PMID 41285728, 2025).
pancreatic cancer (continued). "First, we quantified the expression of EMP1, IGF2BP3 and METTL3 in cell subpopulations of pancreatic cancer by analyzing single-cell sequencing data." (PMID 41285728, 2025). "The interactions between EMP1 and VASP were confirmed using co-immunoprecipitation (Co-IP) assays, and immunofluorescence staining confirmed the colocalization of EMP1 and VASP in pancreatic cancer cells." (PMID 41285728, 2025). "In conclusion, we found that the EMP1-promoted binding of VASP and SMAD7 in pancreatic cancer promotes the activation of the TGF-β/Smads signaling pathway characterized by enhanced phosphorylation of SMAD2/3." (PMID 41285728, 2025). "The experimental results showed that the mRNA expression levels of EMP1, GIPR, SFRP1, CXCL11 and COL17A were significantly high in the pancreatic cancer cell line compared with the controls." (PMID 37547756, 2023). "METTL3 regulated m6A modification, and IGF2BP3 recognized the 3’UTR region of EMP1 mRNA, which could be eliminated by silencing METTL3 in pancreatic cancer cells." (PMID 41285728, 2025). "Moreover, CD8 + T cells, which play an important role in antitumor immunity, were reduced in the infiltration of pancreatic cancer cells that underwent local invasion, high METTL3 and high EMP1 expression." (PMID 41285728, 2025). "Then, the correlation of IGF2BP3, EMP1, and VASP expression was analyzed in the TCGA-PAAD data cells, and results revealed that the expression of EMP1 or IGF2BP3 was positively correlated with VASP in pancreatic cancer." (PMID 41285728, 2025). "Besides, we detected the expression of METTL3 and EMP1 in pancreatic cancer samples serially sectioned with IGF2BP3 in Cohort1 and found that EMP1 was also positively correlated with METTL3 and IGF2BP3." (PMID 41285728, 2025). "In pancreatic cancer cytoskeleton staining, scratch assay, and Transwell migration and invasion assays, we found that the migratory and invasive abilities of pancreatic cancer cells, enhanced by IGF2BP3 overexpression, were significantly reduced by EMP1 depletion." (PMID 41285728, 2025). "Besides, Co-IP analysis illustrated that in pancreatic cancer cells, SMAD7 could bind to the VASP protein, and after knockdown of EMP1 protein in pancreatic cancer cells, the ability of VASP protein binding to SMAD7 was inhibited, and the reverse result was obtained by overexpression of EMP1." (PMID 41285728, 2025).
Cirrhosis (3 papers, 2012 to 2023). A chronic disorder of the liver in which liver tissue becomes scarred and is partially replaced by regenerative nodules and fibrotic tissue resulting in loss of liver function. "EMP1 is also substantially more highly expressed in alcoholic steatosis and cirrhosis than in moderate acute alcoholic hepatitis, according to the set of data (GSE103580; (log2FC = 0.325, P = 0.032)." (PMID 37008256, 2023). "Most notably, up-regulation of caspase-9 and epithelial membrane protein 1 (EMP1) was associated with fibrosis and Bcl-2-related proline-rich protein (BCL2L12) and programmed cell death protein 1 precursor (PDCD1) was associated with cirrhosis." (PMID 27280444, 2016). "In this study, host genes involved in apoptosis such as BCL212 and PDCD1 showed down-regulation in initial fibrosis and significant up-regulation in cirrhosis, whereas, expression levels for CASP9 and EMP1 genes were high at initial stage and were down-regulated in cirrhosis stage." (PMID 22397681, 2012).
head and neck cancer (3 papers, 2022 to 2023). A primary or metastatic malignant neoplasm affecting the head and neck. "In head and neck cancer, overexpression of epithelial membrane protein 1 (EMP1) regulates the expression of Rac1 and NADPH oxidase 1 (NOX 1) through the Hippo-YAP pathway, further promoting RSL3-induced ferroptosis." (PMID 36090052, 2022).
hepatocellular carcinoma (3 papers, 2023 to 2025). A malignant tumor that arises from hepatocytes. "Erlotinib, an EGF receptor inhibitor that can reduce liver fibrosis and the development of hepatocellular carcinoma, suppressed the increased expression of Emp1 in GSE27640." (PMID 37008256, 2023). "Moreover, the roles of EMP1 in the liver are poorly reported, and it is currently only predicted as a potential marker for liver fibrosis and hepatocellular carcinoma by bioinformatics analysis." (PMID 41284206, 2025). "To investigate the expression patterns of EMP1, EMP2, and EMP3 in hepatocellular carcinoma (HCC) and normal liver tissues, we analyzed mRNA expression data from 374 HCC patients obtained from The TCGA database." (PMID 39866225, 2025).
leukemia (3 papers, 2016 to 2025). A malignant (clonal) hematologic disorder, involving hematopoietic stem cells and characterized by the presence of primitive or atypical myeloid or lymphoid cells in the bone marrow and the blood. "Similarly, Emp1 overexpression correlated with enhanced cell proliferation and poor prognosis in B cell precursor ALL leukemia, suggesting an oncogenic function of this gene at least in some hematologic malignancies." (PMID 27690235, 2016).
melanoma (3 papers, 2011 to 2025). A malignant, usually aggressive tumor composed of atypical, neoplastic melanocytes. "For example, of the 16 total genes driving the association between melanoma and nevus count, only two (MTAP and ERVFRD‐3) were shared by all three tissues, and six (MAFF, HEBP1, HTR7P1, EMP1, GPRC5A, C9orf66) were specific to melanocyte." (PMID 38308491, 2024).
renal carcinoma (3 papers, 2023 to 2025). A carcinoma arising from the epithelium of the renal parenchyma or the renal pelvis. "EMP1 +/COL3A1 + fibroblasts are implicated in the bone metastasis of renal cancer and are associated with the activation of EMT genes and the wingless-type MMTV integration site family (WNT) signaling pathway." (PMID 41035074, 2025). "Among different subgroups in renal cancer scRNAseq data, significant correlations between EMP1/COL3A1 and four EMT genes (VIM, SNAI2, TWIST1, and CTNNB1) were found in c9 fibroblasts." (PMID 38187400, 2023). "In renal cancer bone metastasis samples, fibroblasts exhibit increased expression of COL3A1 and EMP1, indicating their involvement in bone metastasis." (PMID 41035074, 2025). "In our results, we also found the involvement of EMP1+/COL3A1+ fibroblasts during the BoM process in breast and renal cancer, which is consistent with previous findings." (PMID 38187400, 2023). "The density of renal cancer cells also affects the sensitivity of cells to ferroptosis, which is achieved by regulating the transcription regulator TAZ-mediated epithelial membrane protein 1 (EMP1)-NOX4 pathway." (PMID 37739961, 2023).
uveal melanoma (3 papers, 2019 to 2022). A melanoma derived from melanocytes of the uveal tract. "In uveal melanoma, the most common intraocular malignancy, EMP1 mRNA levels are higher in class 2 tumors than in class 1 tumors." (PMID 31652725, 2019). "A recent study found that treatment with ICG-001, a molecule that can impair the WNT/β-catenin signaling pathway, has strong anti-cancer activity against uveal melanoma by inhibiting the expression of EMP1 and the mTOR and mitogen-activated protein kinase (MAPK) signaling pathways." (PMID 31652725, 2019).
fetal growth restriction (2 papers, 2020 to 2024). A fetus that does not grow beyond the 10th percentile of conventionally accepted weight for gestational age. "Circulating EMP1 was positively associated with severe placental insufficiency, placental dysfunction, and fetal growth restriction." (PMID 38666946, 2024). "We validated the association between preterm fetal growth restriction and circulating EMP1, NR4A2, and PGM5 mRNA in a cohort from Europe." (PMID 32438913, 2020). "The association between EMP1 and preterm fetal growth restriction appeared strongest." (PMID 32438913, 2020). "In this validation cohort, circulating EMP1 as a lone marker had 65% sensitivity in identifying the presence of preterm fetal growth restriction at 90% specificity, and an AUC of 0.89 (95% CI 0.82–0.97)." (PMID 32438913, 2020). "Thus, we have validated the association between preterm fetal growth restriction and increased circulating mRNA coding NR4A2 and EMP1 (and possibly PGM5) in an independent cohort of samples from another continent." (PMID 32438913, 2020). "Furthermore, EMP1 was correlated with severe clinical parameters that reflect placental insufficiency and was deranged in another cohort of women with preterm fetal growth restriction whose pregnancies ended in stillbirth." (PMID 32438913, 2020). "Combining EMP1 and PGM5 had 72% sensitivity to detect preterm fetal growth restriction at 90% specificity, and an AUC of 0.92 (95% CI 0.86–0.98)." (PMID 32438913, 2020).
head and neck squamous cell carcinoma (2 papers, 2021 to 2022). A squamous cell carcinoma that arises from any of the following anatomic sites: lip and oral cavity, nasal cavity, paranasal sinuses, pharynx, larynx, and salivary glands. "However, the expression level of EMP1 and its functional role in head and neck squamous cell carcinoma (HNSCC) remain unclear to date." (PMID 35432717, 2022).
liver fibrosis (2 papers, 2023 to 2025). "However, emerging evidence indicates that EMP1 expression is upregulated in various forms of liver injury and fibrotic diseases, suggesting its potential role as a biomarker for liver fibrosis." (PMID 41284206, 2025). "Taken together, these bioinformatic data imply that EMP1 might be used as a marker gene during liver fibrosis after injury and may have a potential role in HSCs, however additional validating experiments is needed in the future." (PMID 37008256, 2023). "Given that HSC activation promotes liver fibrosis and MASLD-IRI enhances fibrosis susceptibility without causing immediate fibrosis, we next assessed whether EMP1 silencing mitigates fibrosis in a CCl4-induced model." (PMID 41284206, 2025).
phyllodes tumor (2 papers, 2020 to 2023). A benign, borderline, or malignant fibroepithelial neoplasm arising from the breast and rarely the prostate gland. "With increasing histologic grade, the expression of EMP1, EMP2, and EMP3 decreases in the epithelial component and increases in the stromal component of phyllodes tumors." (PMID 37008256, 2023). "Univariate analysis of the impact of EMP1, EMP2, and EMP3 expression in phyllodes tumors." (PMID 32857809, 2020).
placental insufficiency (2 papers, 2020 to 2024). Failure of the placenta to deliver an adequate supply of nutrients and oxygen to the fetus. "EMP1 mRNA appeared to have the most consistent association with placental insufficiency in all cohorts." (PMID 32438913, 2020). "Of all the circulating mRNA molecules we identified, EMP1 appears the most promising as a marker of placental insufficiency." (PMID 32438913, 2020). "Circulating mRNA EMP1 may be promising as a biomarker of severe placental insufficiency." (PMID 32438913, 2020).
retinoblastoma (2 papers, 2019 to 2022). A malignant tumor that originates in the nuclear layer of the retina. "In retinoblastoma, EMP1 might be the key target of tumor suppressor trefoil factor family peptide 3 (TFF3) signal transduction." (PMID 36217151, 2022). "Taken together, our data strengthen the tumor suppressive function of TFF3 in retinoblastoma cells and emphasize TFF3’s downstream signaling components miR-34a and EMP1 as potential targets for adjuvant RB therapy and drug development strategies." (PMID 31450568, 2019).
Stillbirth (2 papers, 2020 to 2021). Death of the fetus in utero after at least 22 weeks of gestation. "Circulating NR4A2, EMP1, and RCBTB2 mRNA were differentially regulated in another cohort destined for stillbirth, compared to ongoing pregnancies." (PMID 32438913, 2020).
triple-negative breast carcinoma (2 papers, 2025). An invasive breast carcinoma which is negative for expression of estrogen receptor (ER), progesterone receptor (PR), and human epidermal growth factor receptor 2 (HER2). "Collectively, we provide first evidence that EMP1 is downregulated in triple-negative breast cancer and suppresses malignant progression via the PI3K/AKT pathway." (PMID 41458590, 2025). "As expected, EMP1 overexpression significantly downregulated the levels of phosphorylated AKT in MDA-MB-231 triple-negative breast cancer cells." (PMID 41458590, 2025). "To explore the molecular mechanism by which EMP1 modulates triple-negative breast cancer (TNBC) progression, we probed the PI3K/AKT pathway—a key regulator of TNBC pathogenesis." (PMID 41458590, 2025). "Downregulation of EMP1 expression increased the levels of phosphorylated PI3K in MDA-MB-231 triple-negative breast cancer cells." (PMID 41458590, 2025). "In addition, the biological function of EMP1 in triple-negative breast cancer (TNBC) is largely unclear." (PMID 40016223, 2025).
acute myocardial infarction (1 paper, 2022). Necrosis of the myocardium, as a result of interruption of the blood supply to the area. "For example, circMACF1 has an inhibitory effect on acute myocardial infarction via miR-500b-5p and EMP1 (epithelial membrane protein 1)." (PMID 35365168, 2022).
alcoholic hepatitis (1 paper, 2023). Acute hepatitis resulting from ingestion of alcohol. "According to the GSE28619 dataset, hepatic gene expression profiling was examined by microarray in patients with alcoholism (n = 15) and normal livers (n = 7), and EMP1 is considerably higher in alcoholic hepatitis tissues (GSE28619; log2FC = 2.73, P = 1.08 × 10−5)." (PMID 37008256, 2023). "Then, we discovered that EMP1 levels are also elevated in various liver samples after injury, such as the BDL model and alcoholic hepatitis in humans." (PMID 37008256, 2023).
benign ovarian tumors (1 paper, 2023). "Additionally, no discernible variations in EMP1 expression were observed between the group with cisplatin‐sensitive OC and the group with benign ovarian tumors." (PMID 36708070, 2023).
bladder urothelial carcinoma (1 paper, 2024). "Furthermore, EMP1 has been shown in several studies to be a reliable biomarker in cancers such as gastric, colorectal ovarian, bladder urothelial carcinoma and non-small lung carcinoma." (PMID 38324544, 2024).
brain tumors (1 paper, 2008). "Another gene, EMP1 has been associated to highly proliferative cell types in mouse brain tumors." (PMID 18302799, 2008).
breast phyllodes tumor (1 paper, 2020). A benign, malignant, or borderline circumscribed biphasic neoplasm that arises from the breast. "In this study, we aimed to evaluate the expression of EMP1, EMP2, and EMP3 in breast phyllodes tumors (PTs), and to investigate their clinical implications." (PMID 32857809, 2020).
Chlamydia infection (1 paper, 2014). "Our results showed that the impact of Chlamydia infection on apoptosis (BIRC3, EMP1, CHAC1), immune response, host cell structure and cell cycle in EEC is similar to what has been observed in epithelial cells." (PMID 24959205, 2014).
depression (1 paper, 2013). "Two further molecules regulating neurogenesis have been found to be altered in depression: pericentrin 2 (PCNT2) and epithelial membrane protein 1 (EMP1)." (PMID 23384232, 2013).
diabetes (1 paper, 2015). "Among the potential targets of miR-34c-5p, some of the diabetes-related signature genes identified earlier were found, i.e. PTGS2, PDE4B and EMP1 were predicted as targets of miR-34c-5p in three to five algorithms." (PMID 26083362, 2015).